LINC01132 (long independently transcribed non-coding RNA 1132)
Gene: Long non-coding RNA gene on chromosome 1 (234,724,042 to 234,744,590, forward strand). Ensembl gene ENSG00000227630.
Diseases named in the same sentence as LINC01132 in open-access papers:
LINC01132 is named in the same sentence as 5 diseases in open-access papers, as found by Europe PMC text mining. Sharing a sentence is not in itself a finding about the gene and the disease. The quoted sentences say what the papers report.
ovarian carcinoma (3 papers, 2019 to 2024). A malignant neoplasm originating from the surface ovarian epithelium. "LINC01132 was also upregulated as a cancer-promoting factor in epithelial ovarian cancer and predicted poor prognosis." (PMID 38403680, 2024). "LINC01132 is located on chromosome 1q42.3 and regulates pathological mechanisms such as glioblastoma and ovarian cancer." (PMID 38403680, 2024). "Taken LINC00511, LINC01132, MIR762HG and RP11‐83A24.2 for example, ovarian cancer patients with higher LINC00511 and LINC01132 expression levels or lower MIR762HG and RP11‐83A24.2 expression levels had poorer outcome." (PMID 31016892, 2019). "LINC01132 is a long noncoding RNA gene that has been reported to function as an oncogene that relates to the malignant behaviors of cancer cells in hepatocellular carcinoma (HCC) and ovarian cancer." (PMID 37935791, 2024).
hepatocellular carcinoma (2 papers, 2024). A malignant tumor that arises from hepatocytes. "Previous studies have suggested that high expression of LINC01132 has positive implications on the growth and metastasis of hepatocellular cancer cells, and LINC01132 knockdown mediates the therapeutic effect by affecting cell infiltration." (PMID 38403680, 2024).
lung carcinoma (1 paper, 2024). "The aberrated lncRNAs were screened in the GSE98929 dataset, and the upregulation of LINC01132 in the lung cancer samples was further confirmed on the GEPIA website." (PMID 38403680, 2024). "In summary, we evaluated the expression and functional mechanism of LINC01132 in lung cancer, and it was confirmed that LINC01132 is a prominently expressed lncRNA in lung cancer and has extensible potential value as a prognostic biomarker." (PMID 38403680, 2024). "This suggests that lung cancer patients with high expression of LINC01132 have poor prognosis and that LINC01132 may play a regulatory role in the progression of lung cancer." (PMID 38403680, 2024).
cancer (3 papers, 2022 to 2024). A tumor composed of atypical neoplastic, often pleomorphic cells that invade other tissues. "Patients with more than one cancer embolus (p = 0.0032) or larger tumor size (p = 0.0321) had even higher LINC01132 expression levels." (PMID 36071454, 2022). "Moreover, knockdown of LINC01132 significantly decreased cell proliferation (p < 0.001), while LINC01132 overexpression significantly promoted the cancer cells proliferation (p < 0.001)." (PMID 36071454, 2022). "Moreover, LINC01132 exhibited higher copy number amplification across various cancer types." (PMID 36071454, 2022).
tumor (3 papers, 2022 to 2024). "LINC01132 is significantly overexpressed in tumor and associated with poor overall survival of HCC patients, which is mainly driven by copy number amplification." (PMID 36071454, 2022). "We found that LINC01132 exhibited significantly higher expression in tumor patients." (PMID 36071454, 2022).